MMP2 (matrix metallopeptidase 2)
Diseases named in the same sentence as MMP2 in open-access papers (continued):
Sharing a sentence is not in itself a finding about the gene and the disease.
tumor (continued). "Generally, increased expression of MMP-1, MMP-2, MMP-3, MMP-7, MMP-9, MMP-13, and MMP-14 are associated with cancer advancement, which relates to poor cell differentiation, tumor invasion, distant metastasis, and poor prognosis." (PMID 33892690, 2021). "Taken together, serum and even urine levels of circulating MMP-2/-9 can be used as good clinical markers for tumor incidence, cancer stages, and treatment prognosis or success." (PMID 34055644, 2021). "On the contrary, the loss of KLF4 weakened the inhibition of N-cadherin, MMP2, and MMP9, leading to increased tumor cell invasion and migration, thereby affecting survival and prognosis." (PMID 34367275, 2021). "DDR1 is associated with tumor progression and is linked to regulating cell adhesion and migration via modulating the expression of MMPs like MMP1, MMP2, and MMP937,38." (PMID 34837026, 2021). "EMT-related molecules including Twist, Slug and Vimentin and MMP-2 play a crucial role in tumor metastasis and invasion." (PMID 33430870, 2021). "Because the percentages of MMP2/9 overexpression were much higher in tumor cells compared with in stromal cells under the same IHC criteria, we focused on tumoral MMP2/9 and excluded stromal MMP2/9 to keep the homogeneity of eligible studies in present study." (PMID 33568081, 2021). "E-cadherin and vimentin are both EMT related proteins, and MMP-2 plays an important role in tumor invasion and metastasis 16,17." (PMID 33613773, 2021). "Inhibition of XBP1 in TAMs downregulated the expression of pro-tumor cytokines, such as IL-4, IL-6, MMP2 and VEGFA." (PMID 34667145, 2021). "Among other top ascorbate-mediated protein increases were extracellular matrix remodeling proteins such as MMP-2 and TIMP-1 which are associated with tumour metastasis and poor prognosis." (PMID 33799728, 2021). "The upregulation of TAS2R8 and TAS2R10 counteracted gene expression of MMP-2 and P-selectin in tumour tissues, indicating an improved cell adhesion and therefore a reduced metastatic potential." (PMID 34885005, 2021). "Interacting with matrix metalloproteinases (MMPs) (e.g., MMP-2, -3, -7, and -9) and influencing the collagen fiber content within the tumor tissue, this subgroup of cells directly affects such crucial aspects as tumor formation, progression, or metastasis." (PMID 34572905, 2021). "MMP-14 also contributes to the degradation of the extracellular matrix by activating other MMPs, such as pro-MMP-13 and pro-MMP-2, and plays a crucial role in molecular carcinogenesis and tumor growth." (PMID 33946534, 2021). "TGFβ-mediated signaling axis is the principal mediator of EMT initiation and it has been recently revealed that TGFβ type I receptor activates Snail and MMP2 to promote tumor invasion." (PMID 33809973, 2021). "This increased invasiveness is dependent upon a synergistic interaction between MT1-MMP residing within the tumor cells that acts to degrade the surrounding matrix while also activating MMP2, which is secreted from nearby fibroblasts in an inactive form." (PMID 33740019, 2021). "In metastatic cells, laminin promotes activation of matrix metalloproteinase-2 (MMP2), which has a role in tumor cell metastasis." (PMID 33435161, 2021). "Overexpression of MMP2 promotes the metastasis and spread of various tumours and is the most important molecule that directly promotes tumour metastasis." (PMID 34425834, 2021). "Owing to the over-expression of matrix metalloproteinase-2 (MMP-2) in the tumor region, the gelatin can be biodegraded, leading to the shrinkage of nanoparticles, which further benefits the deep penetration." (PMID 33941206, 2021). "Gelatinases, including metalloproteinase 9 (MMP-9) and metalloproteinase 2 (MMP-2), play an important role in the development of malignancies through facilitating tumor invasion, metastasis, growth, cell migration and angiogenesis." (PMID 34071492, 2021).
tumor (continued). "In summary, these findings implicate an important interplay between MT1-MMP from tumor cells and MMP2 from fibroblasts as a key component for ECM remodeling and invasion." (PMID 33740019, 2021). "Since the substrate chosen can be cleaved by MMP-14 or MMP-2, all three tumor lines appeared to be feasible for our studies." (PMID 34620867, 2021). "Depletion of MT1-MMP, the known activator of MMP2, in tumor cells largely blocked matrix remodeling, even in the presence of stromal cell medium." (PMID 33740019, 2021). "The precise contribution of Mmp2 in tumor cells was investigated through modulation of their MMP2 expression." (PMID 34032639, 2021). "Recently, the concept was also extended for monitoring MMP-2/-9 activity in the tumor microenvironment." (PMID 33802262, 2021). "Synergies with nanotechnology are one promising area, best typified by a cleavage-responsive nanosensor based on Gd complexes bound to magnetic nanoparticles, revealing MMP-2 activity in a rodent tumor model." (PMID 33802262, 2021). "In both HCT116 and Caco-2 cells, LMWF enhances the suppressive effects of 5-FU on tumor cell migration through treatment through the c-MET/MMP-2 signaling pathway." (PMID 34360807, 2021). "Several experiments by our group demonstrate that selenite inhibits tumor invasion by blocking MMP-2 and -9 expression, and MSeA inhibits tumor invasion induced by PMA via blocking MMP-2 activation." (PMID 34769276, 2021). "Once the UCNP nanocages arrived at the tumor tissue, the overexpression of the MMP-2 enzyme triggered the release of siRNAs." (PMID 34427999, 2021). "As such, we analyzed the DNA-binding activity of STAT3 to the MMP2 promoter for tumor invasion, and the PD-L1 promoter for tumor metastasis." (PMID 33805840, 2021). "We investigated the role of relevant immune cell populations in controlling MMP2-driven tumor growth." (PMID 34032639, 2021). "Further, the pro-MMP2 from the stromal fibroblasts is activated by MT1-MMP expressed on the tumor cells." (PMID 33740019, 2021). "MMP‐2, as a member of matrix metalloproteinases (MMPs), is vital to the migration and invasion of tumor cells that due to MMP‐2 can degrade the main constituent of membranes (type IV collagen)." (PMID 33552853, 2021). "Recent studies have indicated that MMP2 is highly expressed in many tumors, and its increase promotes proliferation and metastasis, and reduces tumor cell apoptosis." (PMID 34587931, 2021). "Among the different MMPs, MMP-9 and MMP-2 belong to a family of zinc-dependent endo-peptidases which are secreted by stromal and tumor cells as inactive zymogens, and then activated following the cleavage of the pro-domain peptide into their active form." (PMID 34885656, 2021). "Gelatinases (MMP2 and 9) are known to be involved early in the tumor invasion degrading collagen in the basement membrane." (PMID 33809973, 2021). "Due to the high level of MMP-2 in the tumour, the MMP-2 sensitive peptide will be degraded to release the PEG segment, which results in the accumulation of APP-DOX inside the tumour." (PMID 34630113, 2021). "Consistent with our previous data, Mmp2 OE led to the skewing of tumor-specific T cells toward a Th2 phenotype." (PMID 34032639, 2021). "Researchers have found that MMP-2 is over-expressed in ESCC tumor tissues, and TIMP2 is down-regulated in both tissues and serum." (PMID 34778021, 2021). "In the present study, compound C150 significantly inhibited the activity of MMP-2, which is one of the main enzymes responsible for degrading collagen fibers in the tumor stroma." (PMID 34976816, 2021). "CD147, a highly glycosylated protein on the tumor cell surface, having Lewis antigen on its surface promotes CD147 mediated tumor cell adhesion and expression of matrix metalloproteinase-2 (MMP-2)." (PMID 33859913, 2021). "MMP-2 expression contributes to tumor aggressiveness and poor prognosis and induces tumor occurrence." (PMID 34078895, 2021).
tumor (continued). "The inhibition of tumour vascularisation, invasiveness and cell proliferation was observed in mice treated with MMP-2 inhibitor (halofuginone)." (PMID 33923108, 2021). "HPV16 E6 transcripts are also elevated in female mice, a phenomenon which has also been associated with estrogen receptor signaling in this animal model and is likely to contribute to MMP2 overexpression and tumor invasion." (PMID 34684173, 2021). "Studies show that MMP-2 and MMP-9 deficient mice show impaired tumor cell growth and poor metastasis." (PMID 33841500, 2021). "MMP2 and MMP9, also known as Gelatinase A and B, play key roles in the carcinogenesis of BC, with functions in cell proliferation, inflammation, angiogenesis, tumor invasion and metastasis." (PMID 33568081, 2021). "TTN-AS1 silencing restrained OS cell proliferation, migration, invasion, N-cadherin and MMP-2 protein expression, and hindered tumor growth." (PMID 34141611, 2021). "In human OSA, intercommunication between tumor cells and type I collagen mediates MMP-2 synthesis and activation." (PMID 33807419, 2021). "In a subsequent study, authors developed an MMP2-sensitive polymer (PEG2k-pp-PE), to construct Dasatinib micellar NPs with three specific objectives: drug delivery, tumor targeting and sensitization of resistant cancer cells to drug treatments." (PMID 34207175, 2021). "PRO has been shown to inhibit growth, decrease vessel density and lower VEGF, MMP2/9 levels in neuroblastomas and repress tumor growth in hemangiomas through hypoxia-inducible factor-1 alpha (HIF-1α) and STAT3 signaling." (PMID 34790909, 2021). "Of note, the chlorotoxin-based CAR required matrix metalloproteinase 2 (MMP2) expression on the tumor cells for efficient binding." (PMID 34884607, 2021). "The Tat moiety was protected under the long-chain PEG in physiological conditions (low MMP-2 concentration 100 ng·mL−1), while it was exposed after reaching the tumor district (high MMP-2 concentration 100 ng·mL−1)." (PMID 34279392, 2021). "In the study involving large oncosomes (also referred as TEVs) isolated from the LNCaP prostate adenocarcinoma cell line, it was shown that they contained bioactive matrix MMP-2 and -9, key proteases involved in tumor cell invasion." (PMID 33540535, 2021). "MT1-MMP, an activator of pro-MMP-2 expressed on the surface of tumor cells, closely correlates with the invasive phenotype of human tumors." (PMID 34203581, 2021). "The liposomes were responsive to overexpressed MMP2 (matrix-metalloprotease-2) enzymes, resulting in enhanced tumor targeting, internalization and enhanced anti-tumor efficacy both in vitro and in vivo." (PMID 33562376, 2021). "Our studies identified a mechanism by which Mmp2 modulates antitumor activity: ligation of TLR2/4 on APCs promotes tumor infiltration of myelosuppressive populations while reducing tumor infiltrating CD4+ and CD8+ T cells, NK cells, and CD103+ DCs." (PMID 34032639, 2021). "The masking polypeptide and HFt are joined via a peptide sequence that can only be removed by cancer-specific proteases MMP-2/9, selectively expressed in the tumor microenvironment." (PMID 33568214, 2021). "MMP-2 is involved in the degradation of B1 integrins, thus increasing motility and diminishing adhesion of tumor cells." (PMID 34096454, 2021). "In glioma cells, RT-induced secretion of MMP-2/-9 enhanced tumor cell migration in vitro and dissemination in vivo." (PMID 34055644, 2021). "MAPK signalling pathway activated by nicotinic cholinergic receptors (NCRs) can enhance tumour cell proliferation, accompanied by increased expression of MMP2 and MMP28 genes." (PMID 34809653, 2021). "High expression of MMP-2, MMP-9, and both has been associated with tumor progression and poor survival of HCC patients." (PMID 34819565, 2021).
tumor (continued). "STAT3, an important member of the JAK/STAT signaling pathway, is negatively regulated or activated by PLK1, leading to the up-regulation of the downstream gene MMP2, thereby enhancing the aggressiveness of tumor cells." (PMID 34858165, 2021). "These NPs lose their PEG coronas in the presence of MMP-2 in the tumor microenvironment, resulting in shrinkage that facilitates NP cellular uptake." (PMID 34834387, 2021). "A number of studies have found that elevated levels of MMP-2 determines the invasive and metastatic capacity of tumor cells." (PMID 34429501, 2021). "MMPs lacking a transmembrane domain are expressed on the surface of other cells including MMP‐1 on keratinocytes, MMP‐2 on the surface of endothelial cells, fibroblasts, and tumor cells, and MMP‐8 and MMP‐9 on the surface of PMNs." (PMID 33656791, 2021). "MMP‐2 (gelatinase A), which is a type IV collagenase, is involved in the remodelling and degradation of the extracellular matrix and plays a central role in the tumour metastasis, invasion and shortened survival of patients with cancer." (PMID 34528373, 2021). "MMP-1 and MMP-2 were expressed both in tumor cells and normal epithelial cells, but their activity was higher in BCC compared to normal skin." (PMID 34204372, 2021). "The MMP-2-positive area within the tumor periphery was at 54 dpt significantly larger in DH82-CDVai xenografts compared to untreated controls (p < 0.0001) and DH82-UV-CDVai tumors (p = 0.0005)." (PMID 33808256, 2021). "Especially, CS reduced the tumor area and nodules that spread to lung and liver by suppressing MMP-2 and MMP-9." (PMID 33801741, 2021). "Western blot assay demonstrated that the downregulation of ALKBH5 reduced the expression of the tumor metastasis-related proteins matrix metallopeptidase 2 (MMP2), MMP7, and MMP9 in UM cells." (PMID 33428593, 2021). "By performing in vitro experiments, LINC00963 was found to promote CRC cell proliferation, cycle progression, tumor growth, and up-regulated the expressions of MMP-2 and MMP-9." (PMID 33536018, 2021). "We conclude that the significantly decreased APRIL and increased BAFF, IL8 and MMP2 expression were tumor-specific and deserve consideration in the development of new treatments." (PMID 33846436, 2021). "Due to their structural and functional similarities, it is not surprising that multiple studies report co-upregulation of MMP-9 and MMP-2 upon irradiation, leading to increased tumor cell invasiveness, metastasis, and angiogenesis." (PMID 34055644, 2021). "The modification of the MMP-2 cleavable peptide further endowed the nanocages with the ability of tumor responsive drug release, which greatly improved the drug release efficiency and reduced side effects." (PMID 34427999, 2021). "Expression of MMP-2 in the tumor samples increased concomitantly with the progression of CRC clinical stage." (PMID 34429501, 2021). "The levels ratios (tumor vs. control) of APRIL, BAFF, IL-8 and MMP-2 were patient-wise negatively correlated in log scale with CD163 protein expression ratios (tumor/control)." (PMID 33846436, 2021). "Here, we synthesized a tumor microenvironment-sensitive delivery polymer by conjugating HA to cationic PEI along with an MMP-2-sensitive peptide (P; GPLGLAGC) linker (HA-P-PEI) to deliver the PD-L1–siRNA into H1975 cells." (PMID 34078185, 2021). "Many previous studies have demonstrated that Mmp-2 and Mmp-9 are closely related to tumor invasion and metastasis." (PMID 34539418, 2021). "In GC cells, LAMA4 knockdown led to a reduced tumor invasive capability via inhibiting the expression of MMP2, a critical enzyme that degrades ECM." (PMID 34414238, 2021). "CAFs release the matrix metalloproteinase (MMP)-2 as inactive pro-enzyme (pro-MMP-2) in tumor microenvironment." (PMID 33500395, 2021). "MMP2/9 have been widely identified as a group of agitators in tumor metastasis by promoting matrix breakdown to accelerate cell migration when pro-inflammatory mediators stimulated." (PMID 33966042, 2021).
tumor (continued). "Increased expression of CDH2, CTSB, ACTA2, MMP2 and ZEB1 was associated with increased myometrial invasion, and expression of CTSB and MMP9 was significantly associated with tumor recurrence." (PMID 34936030, 2021). "We previously observed that MMP2-stimulated APCs prime T cells toward a Th2 phenotype, which is typically detrimental toward tumor control." (PMID 34032639, 2021). "EMT-related molecules (Twist, Slug, Vimentin and MMP-2) even play an important role in tumor metastasis and invasion." (PMID 33430870, 2021). "In terms of the tumor inhibition rates, histopathology, and inhibition of MMP2 and MMP9, it was observed that although the Hespintor was not as effective as Sorafenib, two factors should be considered." (PMID 33391431, 2021). "The results showed that collagen remodeling takes place in intraepithelial lesions, and SCC shows marked collagenolysis, showing that MMP2 is actively involved in tumor invasion in this model." (PMID 34684173, 2021). "In cancer cells, miR-1 works as a tumor suppressor and can target directly or indirectly a plethora of proteins, including MMP-2, MMP-9, and the antiapoptotic protein BCL2, which is considered one of the main targets of the tumor-suppressive action of miR-1." (PMID 34575852, 2021). "MMP2-expressing cells were found proximal to CD45+ cells, suggesting an interaction between hematopoietic cells that express TLR2 and -4 and MMP2+ tumor or stromal cells." (PMID 34032639, 2021). "Integrins contribute to tumor cells’ invasion by regulating the localization and activity of matrix-degrading proteases, such as matrix metalloprotease 2 (MMP2) and urokinase-type plasminogen activator (uPA)." (PMID 35153410, 2021). "The nanocages were destroyed by the matrix metalloproteinase (MMP)-2 enzymes, which were overexpressed around the tumor tissues by the cleavage of the enzyme-cleavable peptide chain (contained in DNA-5) on the surface of the gold nanocages." (PMID 33627152, 2021). "The present study mainly focused on the protein expression in tumor cells and has excluded MMP2/9 mRNA and protein expression in serum and stromal cells." (PMID 33568081, 2021). "MMP-2 and -12 act on plasminogen to produce angiostatin, an anti-angiogenic component, which suppresses metastasis and tumor growth in lung cancer." (PMID 34912809, 2021). "Since ASPN regulates GC metastasis through activation of EGFR and the ERK-CD44/MMP-2 pathway, it perhaps favourably associates with TGFB1 and activates the signaling pathway to promote tumor growth and progression." (PMID 34379688, 2021). "Following cleavage of the PEG corona by matrix metalloproteinase-2 (MMP-2), the PS penetrated into the deep layers of the tumor for FI and PDT." (PMID 34158855, 2021). "The levels of MMP‐2 and ‐9, which play important roles in tumor cell invasiveness and metastasis, decreased." (PMID 33641229, 2021). "MMP‐2 localizes on the surface of endothelial cells and tumor cells by binding to the αvβ3 integrin or forming a ternary complex with TIMP‐2 bound to MT1‐MMP to promote the migration of these cells." (PMID 33656791, 2021). "The underpinning protumourigenic USP22 on tumour cells was EMT induction, exhibiting loss of epithelial E-cadherin and gain of mesenchymal vimentin, with upregulation of MMP2/9 invasive markers in CCA cell lines." (PMID 34226501, 2021). "In contrast, knockdown of Mmp2 slowed tumor growth and enhanced T cell proliferation and NK cell recruitment." (PMID 34032639, 2021). "MMP‐2 and TGF‐RI in the circulating tumour cells of PC patients are closely associated with disease severity." (PMID 33683827, 2021). "They suggested that miR-29b exerted its anti-angiogenic activity by inhibiting the expression of MMP-2 in tumor cells and suppressing VEGFR-2 signaling in endothelial cells." (PMID 34095461, 2021).